PKMYT1 (protein kinase, membrane associated tyrosine/threonine 1)
Description:
Acts as a negative regulator of entry into mitosis (G2 to M transition) by phosphorylation of the CDK1 kinase specifically when CDK1 is complexed to cyclins. Mediates phosphorylation of CDK1 predominantly on 'Thr-14'. Also involved in Golgi fragmentation. May be involved in phosphorylation of CDK1 on 'Tyr-15' to a lesser degree, however tyrosine kinase activity is unclear and may be indirect.
Synonyms: MYT1; PPP1R126
Tractability: Small molecule: a structure with a bound ligand is known; a high-quality ligand is known; it has a high-quality binding pocket; it belongs to a druggable protein family. Antibody: UniProt places it where antibodies can reach, with high confidence. PROTAC: it is named in the literature on targeted protein degradation; ubiquitination databases record sites on it; a small molecule that binds it is known.
Target class: Other protein kinase WEE family; Enzyme; Other protein kinase group; Protein Kinase; Kinase
Chemical probes: lunresertib
Gene: Protein-coding gene on chromosome 16 (2,968,024 to 2,980,813, reverse strand). Ensembl gene ENSG00000127564.
Subcellular location: Endoplasmic reticulum membrane; Golgi apparatus membrane
Subcellular location (Human Protein Atlas): Golgi apparatus; Nucleoli; Nucleoplasm
Pathways (Reactome):
Cell Cycle: Cyclin A/B1/B2 associated events during G2/M transition; G2/M DNA replication checkpoint; Polo-like kinase mediated events
Gene Ontology:
Molecular function: kinase activity; protein binding; protein serine/threonine kinase activity; protein kinase activity; ATP binding; protein serine kinase activity
Biological process: negative regulation of G2/M transition of mitotic cell cycle; G2/M transition of mitotic cell cycle; meiotic cell cycle; mitotic cell cycle; negative regulation of G2/MI transition of meiotic cell cycle; regulation of cyclin-dependent protein serine/threonine kinase activity; regulation of mitotic nuclear division
Cellular component: endoplasmic reticulum membrane; Golgi apparatus; Golgi membrane; membrane; cytoplasm; cytosol; endoplasmic reticulum; nucleoplasm; nucleus
Genetic constraint (gnomAD): Loss-of-function variants: 33 observed, 38.84 expected, observed/expected ratio (o/e) 0.85, 90% interval 0.64 to 1.14. The synonymous counts are far from expectation, so gnomAD's model fits this gene poorly and the ratio says little. Missense variants: 673 observed, 601.21 expected, observed/expected ratio (o/e) 1.12, 90% interval 1.05 to 1.19. Synonymous variants: 330 observed, 259.44 expected, observed/expected ratio (o/e) 1.27, 90% interval 1.16 to 1.39.
Homologues: Orthologues: macaque PKMYT1 (99% identical), chimpanzee PKMYT1 (94% identical), pig PKMYT1 (90% identical), dog PKMYT1 (89% identical), rat Pkmyt1 (88% identical), guinea pig PKMYT1 (88% identical), mouse Pkmyt1 (88% identical), rabbit PKMYT1 (77% identical), tropical clawed frog pkmyt1 (50% identical), zebrafish pkmyt1 (40% identical), Drosophila melanogaster Myt1 (35% identical), Caenorhabditis elegans wee-1.3 (34% identical), and 1 more. Paralogues in human: WEE1 (26% identical), WEE2 (26% identical), EIF2AK4 (22% identical), STK35 (18% identical), EIF2AK1 (17% identical), EIF2AK3 (17% identical), EIF2AK2 (16% identical), PDIK1L (13% identical).
Diseases named in the same sentence as PKMYT1 in open-access papers:
PKMYT1 is named in the same sentence as 50 diseases in open-access papers, as found by Europe PMC text mining. Sharing a sentence is not in itself a finding about the gene and the disease. The quoted sentences say what the papers report.
breast carcinoma (14 papers, 2019 to 2025). "This study establishes SELENOP and PKMYT1 as key metabolic-immune regulators reprogramming the breast cancer microenvironment, serving as diagnostic biomarkers and therapeutic targets." (PMID 40821907, 2025). "SELENOP and PKMYT1 are novel immunomodulatory factors related to multiple pathological indicators of breast cancer and can be used as diagnostic biomarkers." (PMID 40821907, 2025). "In this study, we found that PKMYT1 expression was significantly elevated in breast cancer tissues and demonstrated high diagnostic accuracy for breast cancer, suggesting its potential diagnostic value." (PMID 40821907, 2025). "Based on Kaplan-Meier plotter database analysis, PKMYT1 overexpression is also associated with a poor prognosis in breast cancer patients." (PMID 38291367, 2024). "Our study showed that ASPM, INHBA, NUF2, ORC6, UBE2T and PKMYT1 are associated with cell proliferation, and the expressions of these genes were also elevated in our breast cancer tissue transcriptome." (PMID 31182966, 2019). "We employed cBioPortal to evaluate the frequency of changes in PKMYT1 mutations in breast cancer." (PMID 31837068, 2020). "The mutations of PKMYT1 in breast cancer were analysed using the COSMIC database." (PMID 31837068, 2020). "A proteogenomic analysis of 22 patient-derived xenografts (PDXs) from ER+ breast cancer identified PKMYT1 as an estradiol (E2)-regulated gene, with intrinsic expression in cases where proliferation was E2-independent." (PMID 40244377, 2025). "PKMYT1 expression was positively correlated with poor prognosis in various human cancers, such as esophageal squamous cell carcinoma and breast cancer." (PMID 40702552, 2025). "A proteogenomic analysis based on patient-derived xenografts (PDX) from 22 ER + breast cancer patients suggested that PKMYT1 is a WEE1 homolog." (PMID 40821907, 2025). "PKMYT1 has been identified as critical for breast cancer cell line survival, suggesting its potential as a viable strategy for therapeutic intervention in breast cancer patients." (PMID 38291367, 2024). "Kaplan–Meier survival analysis and log-rank tests were used to determine the prognostic significance of expression of the three genes, VEGFD, TSLP, and PKMYT1, in patients with breast cancer." (PMID 35472078, 2022). "Accordingly, three consistently relevant genes (i.e., VEGFD, TSLP, and PKMYT1) were selected for the diagnosis of breast cancer." (PMID 35472078, 2022). "For example, the PKMYT1 is negatively correlated with the other 13 genes in breast cancer data, and MED8 is positively correlated with the other four genes." (PMID 36551179, 2022). "At present, several studies have reported some degree of variation about the PKMYT1 gene in the development and progression of multiple tumor, including esophageal squamous cell carcinoma, prostate cancer, breast cancer, liver and colorectal carcinomas." (PMID 34959223, 2021). "PKMYT1, KIF4A, and CDC25C were associated with GO in terms of BPs; previous studies also revealed the overexpression of these genes in breast cancer." (PMID 34834441, 2021). "Our study has revealed that PKMYT1 is the only overexpressed member of WEE family kinases in breast cancer tissues, suggesting its predominant role in monitoring G2/M transition in breast cancer cell division." (PMID 31837068, 2020). "Looking into the relationship between PKMYT1 and breast cancer subtypes, we found that RFS was highly affected by the expression levels of PKMYT1 as shown by KM plotter analysis." (PMID 31837068, 2020).
breast carcinoma (continued). "Collectively, this study demonstrates that overexpression of PKMYT1 is always found in breast cancer and predicts unfavourable prognosis, implicating it as an appealing therapeutic target for breast carcinoma." (PMID 31837068, 2020). "Collectively, these data suggest an essential role of PKMYT1 in regulating cell proliferation in breast cancer." (PMID 31837068, 2020). "The mining of GEPIA database further confirmed that PKMYT1 was the only member of WEE family kinases unregulated in breast cancer (BRCA) tissues in relative to normal tissues." (PMID 31837068, 2020). "In this work, we applied a wide range of integrated bioinformatics approach to assess the importance of PKMYT1 by analysing the expression, potential function and prognostic impact of PKMYT1 in human breast cancer." (PMID 31837068, 2020). "In this study, we used a set of bioinformatic tools to jointly analyse the expression of WEE family kinases and investigate the prognostic value of PKMYT1 in breast cancer." (PMID 31837068, 2020). "The results indicated that PKMYT1 is the only frequently overexpressed member of WEE family kinases in breast cancer." (PMID 31837068, 2020). "Secondly, the mechanisms of SELENOP and PKMYT1 in the occurrence and development of breast cancer remain unclear, which will be the focus of subsequent experimental research." (PMID 40821907, 2025). "In contrast, PKMYT1 displays a distinct substrate specificity towards CDK1 and is associated with enhanced metastatic potential and diminished overall survival in colorectal and breast cancers, highlighting its role as a potential prognostic biomarker." (PMID 40664640, 2025). "In this study, FunRich tool analysis revealed that the biological pathway for co-expressed genes with the PKMYT1 gene is cell cycle and DNA replication, indicating that overexpression of this gene could develop breast cancer tumorigenesis." (PMID 38291367, 2024). "Furthermore, the COSMIC database analyzed the mutations of the CACNG4, PKMYT1, EPYC, and CHRNA6 genes in breast cancer." (PMID 38291367, 2024). "In addition, three stable relevant genes, namely VEGFD, TSLP, and PKMYT1, were chosen for the diagnosis of breast cancer." (PMID 35472078, 2022). "We propose that PKMYT1 could be a promising molecular target for the diagnosis and treatment of breast cancer." (PMID 31837068, 2020). "Due to the difficulty in treatment of breast carcinoma and the importance of G2/M checkpoint for cancer cell survival, we speculate that PKMYT1 may be an attractive molecular target for treatment of breast cancer." (PMID 31837068, 2020). "We collected breast cancer tissue samples from 60 volunteers and performed IHC experiments to validate the expression of SELENOP, PKMYT1 and immune checkpoints in BRCA tissue." (PMID 40821907, 2025). "Based on METABRIC database, CACNG4, PKMYT1, and CHRNA6 exhibited differential expression in breast cancer tissues compared to normal tissues." (PMID 38291367, 2024). "We propose that CACNG4, PKMYT1, and CHRNA6 hold promise as potential targets for both the diagnosis and treatment of breast cancer, while EPYC has the potential to be used only as an effective diagnostic biomarker." (PMID 38291367, 2024). "Through bioinformatics analysis and qRT-PCR validation, we confirmed the upregulation of CACNG4, PKMYT1, EPYC, and CHRNA6 in breast cancer." (PMID 38291367, 2024). "PKMYT1, MYBL2, and CDC20 participate in GO terms of the most upregulated KEGG processes and are involved in the development of breast cancer." (PMID 34834441, 2021). "The PKMYT1 gene, as a member of WEE family kinases, participates in G2 checkpoint surveillance and probably links with tumorigenesis, but its role in breast cancer remains largely unclear." (PMID 31837068, 2020). "In summary, we have confirmed the up‐regulation of PKMYT1 and its partner, PLK1, in breast cancer and validated their importance as prognostic factors." (PMID 31837068, 2020).
breast carcinoma (continued). "The top differentially expressed genes (unadjusted P ≤ .001) were all upregulated and included KIFC1 (OMIM 603763), FAM83D (OMIM 618380), UBE2C (OMIM 605574), CLDN4 (OMIM 602909), GRB7 (OMIM 601522), and PKMYT1 (OMIM 602474), each of which have previously reported roles in breast cancer progression." (PMID 34714340, 2021). "Through our analysis, PKMYT1 expression levels were significantly correlated with ER‐, PR‐, HER2+, Basal‐like status and TNBC subtypes, consistent with the indication of poor prognosis in patients with breast cancer." (PMID 31837068, 2020). "Therefore, VEGFD and TSLP could be used to predict prognosis in patients with breast cancer, whereas PKMYT1 is not suitable for this purpose." (PMID 35472078, 2022). "Interestingly, PLK1 has been proposed to be the functional partner of PKMYT1 in regulating cell cycle, and PLK1 is also closely related to breast cancer, implying that PLK1 and PKMYT1 may play an cooperative role in the development of breast cancer." (PMID 31837068, 2020). "The expression of PKMYT1, but not of WEE1 and WEE1B, was significantly elevated in several solid tumours, especially in breast cancer and colorectal cancer." (PMID 31837068, 2020). "Based on qRT-PCR analysis conducted on 55 breast cancer patients and normal cases, it was observed that CACNG4, PKMYT1, EPYC, and CHRNA6 mRNA exhibited significantly higher expression levels in breast cancer tissues (BCT) compared to non-tumoral adjacent tissues (NTAT) (P < 0.0001)." (PMID 38291367, 2024).
hepatocellular carcinoma (14 papers, 2019 to 2025). A malignant tumor that arises from hepatocytes. "Genes, such as SPC24 and PKMYT1, are linked with the invasion of hepatocellular carcinoma cells, but these genes may be important for the invasion of BRCA cells." (PMID 31311202, 2019). "Recent studies have shown that PKMYT1 expression is increased in hepatocellular carcinoma (HCC), non‐small cell lung cancer (NSCLC), and pancreatic ductal adenocarcinoma (PDAC) and is associated with poor survival probability." (PMID 40279509, 2025). "PKMYT1 has exhibited to be overexpressed in various types of cancer, including hepatocellular carcinoma, as well as promoting tumor progression." (PMID 39619613, 2024). "Beta-catenin/TCF signaling can be activated by PKMYT1 to promote cell invasion and migration in hepatocellular carcinoma." (PMID 35114989, 2022). "In hepatocellular carcinoma, PKMYT1 contributes to the enhanced cell growth and motility through the activation of the beta-catenin/TCF signaling." (PMID 35461324, 2022). "PKMYT1 is a crucial promoter in the development of hepatocellular carcinoma, and overexpression of PKMYT1 indicates a poor prognosis and enhances proliferation and tumorigenesis in non-small cell lung cancer." (PMID 32180804, 2020). "WEE1 and PKMYT1 are also over-expressed in solid tumors, including hepatocellular carcinoma, colon cancer, glioblastoma, non-small-cell lung cancer (NSCLS), neuroblastoma, and gastric cancers." (PMID 32958072, 2020). "However, there have been no reports of dual-targeting inhibitors for protein kinase membrane-associated tyrosine/threonine 1 (PKMYT1) and histone deacetylase 2 (HDAC2), which are critical targets for hepatocellular carcinoma treatment." (PMID 39619613, 2024). "Studies have demonstrated that PKMYT1 might be a therapeutic target in hepatocellular carcinoma and neuroblastoma." (PMID 35472078, 2022). "Previous studies have shown that PKMYT1 positively regulates EMT in hepatocellular carcinoma cells." (PMID 34959223, 2021). "Data have shown that PKMYT1 plays an essential oncogenic role in colorectal cancer and hepatocellular carcinoma, and it may serve as a good therapeutic target for cancer treatment." (PMID 32944406, 2020). "Solid tumors, including hepatocellular carcinoma and colon cancer, exhibit elevated expression of WEE1 and PKMYT1." (PMID 40893386, 2025). "Previous studies have also demonstrated that PKMYT1 upregulation promotes the malignancies of glioblastoma, hepatic carcinoma, and colorectal cancer without deciphering the exact molecular mechanisms." (PMID 34856993, 2021).
gastric cancer (9 papers, 2017 to 2025). A primary or metastatic malignant neoplasm involving the stomach. "Interfering with ALKBH5 expression in gastric cancer cells facilitated metastasis by upregulating Protein kinase, membrane-associated tyrosine/threonine 1(PKMYT1)." (PMID 39791162, 2025). "Demethylase ALKBH5 inhibited the metastatic ability of gastric cancer cells through negative regulation of the expression of protein kinase, membrane-associated tyrosine/threonine 1 (PKMYT1), a member of the serine/threonine protein kinase family." (PMID 38856795, 2024). "For example, ALKBH5 serves as a suppressor for the metastasis of gastric cancer by downregulating the expression of protein kinase and membrane-associated tyrosine/threonine 1 (PKMYT1) in an IGF2BP3-m6A-mediated manner." (PMID 35804965, 2022). "IGF2BP3, acting as an m6A reader, recognized an m6A modification on PKMYT1 mRNA, enhancing its stability and promoting the invasion and migration of gastric cancer cells." (PMID 39791162, 2025). "Studies have revealed that the downregulation of the demethylase ALKBH5 leads to increased expression of PKMYT1 in gastric cancer." (PMID 38570712, 2024). "For example, a decreased expression of ALKBH5 was detected in GC samples, and ALKBH5 expression was correlated with clinical tumor distal metastasis and lymph node metastasis, while the demethylase ALKBH5 suppressed cell invasion of gastric cancer via the PKMYT1 m6A modification." (PMID 38745044, 2024). "For instance, the m6A modification of PKMYT1 by ALKBH5, a demethylase in gastric cancer was demonstrated to suppress cell invasion." (PMID 40069867, 2025). "Targeting IGF2BP3 in gastric cancer HGC-27 cells resulted in a significant downregulation of PKMYT1 expression, highlighting the potential role of the ALKBH5/PKMYT1/IGF2BP3 regulatory signaling pathway in gastric cancer metastasis." (PMID 38856795, 2024).
esophageal squamous cell carcinoma (8 papers, 2020 to 2025). Esophageal squamous cell carcinoma (ESCC) is a type of esophageal carcinoma (EC) that can affect any part of the esophagus, but is usually located in the upper or middle third. "In esophageal squamous cell carcinoma, PKMYT1 promotes cellular proliferation, migration and infiltration through activation of the AKT/mTOR signaling pathway." (PMID 36747547, 2023). "Recent studies have shown that PKMYT1 contributes to tumor progression via AKT/mTOR signaling pathway in esophageal squamous cell carcinoma." (PMID 36793346, 2022). "PKMYT1, a partner of the serine/threonine protein kinase family, was considered as a poor prognosis marker among many different types of tumors, such as glioblastoma, ovarian cancer, prostate cancer, and esophageal squamous cell carcinoma." (PMID 35114989, 2022). "In addition, studies have shown that PKMYT1 promotes tumor progression of esophageal squamous cell carcinoma by activating AKT signaling pathway." (PMID 35461324, 2022). "Moreover, in esophageal squamous cell carcinoma (ESCC) cell lines and primary cells, the expression of PKMYT1 is associated with and regulates the activation of the AKY/mTOR pathway." (PMID 32958072, 2020).
non-small cell lung carcinoma (8 papers, 2020 to 2024). A group of at least three distinct histological types of lung cancer, including non-small cell squamous cell carcinoma, adenocarcinoma, and large cell carcinoma. "Meanwhile, PKMYT1 also promotes carcinogenesis of non-small cell lung cancer through the Notch signaling pathway." (PMID 35461324, 2022). "In non-small-cell lung cancer (NSCLC), they found that the lncRNA PKMYT1AR sequesters the tumor suppressor miR-485-5p, thus determining the efficient translation of the oncogenic protein kinase, membrane-associated tyrosine/threonine 1 PKMYT1." (PMID 36768150, 2023).